RNU6-1196P (RNA, U6 small nuclear 1196, pseudogene)
Gene: Small nuclear RNA gene on chromosome 4 (153,265,662 to 153,265,755, reverse strand). Ensembl gene ENSG00000252030.
Homologues: Orthologues: chimpanzee U6 (100% identical), macaque U6 (98% identical), rabbit U6 (84% identical), guinea pig U6 (77% identical). Paralogues in human: RNU6-19P (87% identical), RNU6-35P (87% identical), RNU6-140P (86% identical), RNU6-17P (86% identical), RNU6-18P (86% identical), RNU6-22P (86% identical), RNU6-25P (86% identical), RNU6-31P (86% identical), RNU6-34P (86% identical), RNU6-43P (86% identical), RNU6-49P (86% identical), RNU6-761P (86% identical), and 1285 more.